BEST1 (bestrophin 1)
Diseases named in the same sentence as BEST1 in open-access papers (continued):
Sharing a sentence is not in itself a finding about the gene and the disease.
retinal disorder (26 papers, 2009 to 2026). Any disease or disorder of the retina. "Best1 channel was originally identified in the retinal pigment epithelium, and its mutations have been demonstrated to underlie several retinopathies." (PMID 36555501, 2022). "This iPSC-RPE- based model retains the patients’ genetic background and thus has direct relevance to BEST1-associated retinal disorders, but is limited by the availability of patient samples." (PMID 34061021, 2021). "BEST1 mutations are usually associated with dominant retinal disorders, and therefore homozygous or compound heterozygous mutations are rare." (PMID 22162627, 2011). "To date, over 370 variants have been identified among BEST1-associated retinopathies." (PMID 37041514, 2023). "These properties of Best1-channel lead to the hypothesis that distorted regulation of intracellular Ca2+ signaling and/or pH homeostasis may underlie the Best1 mutation-related retinopathies (for recent review,)." (PMID 36555501, 2022). "More than 200 mutations in Best1 gene are known to be linked with different retinopathies." (PMID 36555501, 2022). "Nevertheless, these findings suggest that cone-specific functional decline may be an intrinsic feature of BEST1-related retinopathies." (PMID 40327408, 2025). "While there is no question that mutations in BEST1 cause retinal disorders, the specific function of the protein, and some of the pathways leading from mutant gene to disease, are not well understood." (PMID 39774293, 2025). "Mutation in the BEST1 gene might result in abnormal functioning of the protein bestrophin-1, an anion channel in the RPE, leading to a variety of retinopathies." (PMID 35885980, 2022). "It is still not known how different mutations in BEST1 lead to clinically distinct retinopathies." (PMID 34327816, 2022). "To validate the novel genetic testing tool for retinal disorders, we used four DNA samples from families, in which we had previously identified different types of mutations by Sanger sequencing: one 1 bp duplication and one 1 bp deletion in PRPF31 and missense mutations in TRPM1 and BEST1." (PMID 22277662, 2012). "To date, there is no specific treatment or surgical management for BEST1-related retinopathies." (PMID 24143172, 2013).
autosomal dominant disease (6 papers, 2012 to 2024). Autosomal dominant form of disease. "For example, in the pediatric study from the United Arab Emirates, RS1 (X-linked) and BEST1 (usually associated with autosomal dominant disease) also featured in a number of families." (PMID 32423767, 2020). "When detected in younger patients, VLs usually occur in the setting of Best macular dystrophy (Best disease), an autosomal dominant disease associated with a mutation in bestrophin 1 (BEST1)." (PMID 27190637, 2016). "Best’s vitelliform dystrophy, or Best disease, is an autosomal dominant disease affecting as many as 1 in 18,000, and is caused by mutations in the RPE-specific calcium-activated chloride channel Bestrophin 1 (BEST1)." (PMID 39011458, 2024). "It is most commonly an autosomal dominant disease, caused by a mutation in the BEST1 gene, which encodes bestrophin-1, a transmembrane protein located on the basolateral aspect of RPE cells." (PMID 31795241, 2019).
tumor (6 papers, 2020 to 2025). "The evidence that BEST1 expression of monocytes associated with tumor education led to our exploration of the mediating mechanism." (PMID 37088729, 2023). "The study emphasized the use of BEST1 expression as HNSCC marker, since it was overexpressed only in tumor-associated mononuclear cells." (PMID 40862737, 2025). "We described how HNSCC tumor cells affect the expression, regulation, and function of chloride channel protein BEST1 in TIMs." (PMID 37088729, 2023). "We found that BEST1 was mainly expressed on monocytes (CD14+) and tumor‐associated macrophages (TAMs) (CD68+) in the TME of HNSCC patients, and the positive ratio of BEST1 expression in cancer is significantly elevated than that in adjacent normal tissue." (PMID 37088729, 2023). "We found these GFP labeled‐tumor‐infiltrating monocytes could be detected in peripheral blood both at 24 and 72 h after injection, and BEST1 expression was significantly increased on these monocytes at 72 h after injection." (PMID 37088729, 2023). "Tumor growth status demonstrated that BEST1 on macrophages promotes tumor development in vivo." (PMID 37088729, 2023). "Here, we highlighted BEST1 as a functional impress of the crosstalk between tumor cells and TIMs." (PMID 37088729, 2023). "Interestingly, in addition to the regulation of tumor cells, BEST1 facilitates the motility of monocytes, which contributes to the migration of educated monocytes back into circulation." (PMID 37088729, 2023). "This could explain the clinical observation of the consistent existence of BEST1 positive monocytes in peripheral blood and tumor tissue." (PMID 37088729, 2023). "Since monocytes can be recruited into the TME during tumorigenesis, and that in peripheral blood have transcriptional landscape related to tumor, we hypothesized that monocyte could increase the expression of BEST1 and could reflux back into peripheral blood after being influenced by TME." (PMID 37088729, 2023). "To explore the correlation between high expression of BEST1 monocytes in peripheral blood and tumor‐infiltrated monocytes, we performed scRNA‐seq data analysis of HNSCC tumor tissue (GSE103322) and paired carcinoma and adjacent tissue sections staining." (PMID 37088729, 2023). "This is due to monocyte education by tumor cells, in which tumoral VEGF‐A upregulates BEST1 expression on monocytes through the MEK‐ERK‐ELK1 pathway." (PMID 37088729, 2023). "Precisely, tumoral VEGF‐A up‐regulates BEST1 expression on monocytes through the MEK1/2‐ERK1/2‐ELK1 pathway, which improves secretion of cytokines IL‐6 and IL‐8, leading to the promotion of tumor cell proliferation." (PMID 37088729, 2023). "In our research, we identified BEST1 as a marker gene in peripheral blood monocytes of the HNSCC cohort dataset (GSE139324), which can potentially monitor tumor progression." (PMID 37088729, 2023). "Furthermore, the reduced levels of L-lactic acid slow tumour progression through histone H4K16 lactylation and regulate the expression of the BEST1, GRAMD4, and MBD6 genes, with this mitochondrial effector serving as an apoptotic signal induced by E2F1." (PMID 41249152, 2025). "Furthermore, to examine the impact of macrophage BEST1 on tumor development in vivo, a mixture of THP‐1 with BEST1 overexpression or knockout and FaDu cells at a ratio of 1:5 was implanted subcutaneously to the flanks of nude mice." (PMID 37088729, 2023).
autosomal recessive disease (2 papers, 2013 to 2022). Autosomal recessive form of disease. "Canine multifocal retinopathy (cmr), a spontaneous, early-onset autosomal recessive disease caused by mutations in the BEST1 dog ortholog, recapitulates the full spectrum of clinical, genetic and histological features observed in BEST1-affected patients." (PMID 24143172, 2013).
cancer (2 papers, 2020 to 2023). A tumor composed of atypical neoplastic, often pleomorphic cells that invade other tissues. "The discovery of BEST1 positive monocytes as a potential biomarker for HNSCC implied a new path to search cancer biomarkers." (PMID 37088729, 2023). "BEST1, UCP2 and FXYD1 are genes associated with nutrient and energy transport that have previously been identified as upregulated in cancer cells." (PMID 32051475, 2020). "The innovation of our research is the discovery of a BEST1 upregulated subset in peripheral monocytes in HNSCC patients, which is resulted from cancer education through VEGF‐A secretion." (PMID 37088729, 2023).
cardiovascular disease (1 paper, 2024). "We also observed that rs1109748, located in the BEST1 gene, is associated with plasma omega-3 polyunsaturated fatty acid levels, which are related to cardiovascular disease risk and cognitive function in the brain." (PMID 40040643, 2024).
neurological disorders (1 paper, 2023). "As discussed in the last section, multiple chloride channels such as VRAC and Best1 have been suggested to modulate the release of excitatory amino acids, highlighting their roles in neuronal function impairments during neurological disorders and the therapeutic value of chloride-channel modulators." (PMID 36935741, 2023).
BEST1 also shares sentences with these, for which no sentence is quoted: vitelliform macular dystrophy (11 papers); cataract (4); Leber congenital amaurosis (4); retinitis pigmentosa 50 (4); myopia (3); achromatopsia (2); deafness (2); depression (2); melanoma (2); multifocal best vitelliform macular dystrophy (2); androgen insensitivity syndrome (1); aniridia (1); Anxiety (1); autosomal dominant retinitis pigmentosa (1); brain cancer (1); brain diseases (1); Bull's eye maculopathy (1); central areolar choroidal dystrophy (1); channelopathies (1); cholangiocarcinoma (1); chorioretinal degeneration (1); choroideremia (1); congenital toxoplasmosis (1); degenerative disease of (1); early onset retinal dystrophy (1); Familial exudative vitreoretinopathy (1); inherited macular dystrophies (1); injury (1); lysosome storage disease (1); macular oedema (1).
A further 10 diseases each share a sentence with BEST1 in 1 paper.